APC (APC regulator of Wnt signaling pathway)
Diseases named in the same sentence as APC in open-access papers (continued):
Sharing a sentence is not in itself a finding about the gene and the disease.
adrenal tumors (2 papers, 2022 to 2024). "Most of the variants in our patients with adrenal tumours involve frameshift or premature stop codons, typical of pathogenic variants described in APC in the literature and on the LOVD and ClinVar databases." (PMID 39227904, 2024). "The prevalence of adrenal tumours among patients with pathogenic or likely pathogenic APC mutations in this study (26.7%) is so far the highest." (PMID 39227904, 2024). "The hormonal functions of patients with pathogenic APC variants and adrenal tumours can be investigated with routine testing in further research." (PMID 39227904, 2024). "The prevalence of adrenal tumours among patients with pathogenic and likely pathogenic APC mutations in our cohort is likely to be twice to three times higher than the general population prevalence reported from international population-based studies." (PMID 39227904, 2024). "This study aims to investigate the characteristics of adrenal tumours in patients with pathogenic or likely pathogenic APC variants and explore the hormonal function of these patients." (PMID 39227904, 2024). "This study aims to investigate the characteristics of adrenal tumours in patients with pathogenic or likely pathogenic APC variants and the degree of adrenal hormonal testing among these patients." (PMID 39227904, 2024). "In our cohort, the prevalence of adrenal tumours among patients with pathogenic and likely pathogenic APC mutations is at least twice to three times higher than the general population prevalence reported from international population-based studies." (PMID 39227904, 2024). "Given the increased prevalence of adrenal tumours among those with pathogenic APC variants, future research can investigate the functional consequences of these adrenal tumours." (PMID 39227904, 2024). "Rather than regarding adrenal tumours as an extraintestinal manifestation of FAP, we focus on whether the pathogenicity of APC variants would affect the formation of adrenal tumours." (PMID 39227904, 2024). "Thus, it is difficult to assess the pattern of hormonal function for patients with pathogenic APC variants and adrenal tumours." (PMID 39227904, 2024). "However, a correlation of APC inactivating mutations and elevated cortisol levels has been already previously reported for patients with adrenal tumors." (PMID 35563746, 2022). "The hormonal functions of patients with pathogenic APC variants and adrenal tumours should be investigated in further research to better understand whether there are any clinical endocrine implications of the increased prevalence of adrenal tumours in these patients." (PMID 39227904, 2024). "More data on adrenal tumours in classic FAP patients with non-pathogenic APC variants is needed, like in those with MUTYH and HTHL1 variants." (PMID 39227904, 2024).
Anaplastic thyroid cancer (2 papers, 2020 to 2023). "Evidence showed the effect of several genetic variants, including catenin (cadherin‐associated protein), beta 1, AXIN1, and APC, and chromosomal abnormalities in the molecular pathogenesis of Anaplastic thyroid cancer." (PMID 36510340, 2023). "Furthermore, APC mutations have been observed in anaplastic thyroid carcinomas as well." (PMID 31758407, 2020).
aneurysm (2 papers, 2020 to 2022). Bulging or ballooning in an area of an artery secondary to arterial wall weakening. "Moreover, the protein expression of APC was decreased in the brain of intra-cranial aneurysm type of patients, independently of biological sex and age, and was associated to the intra-cranial aneurysm diameter." (PMID 33071819, 2020).
Anxiety (2 papers, 2023 to 2024). Intense feelings of nervousness, tension, or panic often arise in response to interpersonal stresses. "β-Catenin has a distinct role in alleviating anxiety in adolescence; however, it undergoes degradation by the degradation complex Axin and APC." (PMID 38584231, 2024).
Appendiceal adenocarcinoma (2 papers, 2020 to 2025).
atrophic gastritis (2 papers, 2015 to 2025). "Moreover, the cytoplasmic and nuclear accumulation of β-catenin could be observed in premalignant lesions (atrophic gastritis and IM), and increased β-catenin mRNA levels and mutational alterations of the APC and β-catenin gene are present in intestinal-type GC." (PMID 25962957, 2015).
basal cell carcinoma (2 papers, 2017 to 2025). A carcinoma involving the basal cells. "It is interesting to note that the top known dysregulated pathways in BCC, like the hedgehog signaling pathway, basal cell carcinoma pathway, and Notch signaling pathway, had statistically significant interactions with STR somatic mutations in APC and BRAF." (PMID 40427167, 2025).
breast fibroadenoma (2 papers, 2021 to 2023). "The results showed that organoids generally retained the genomic structure of the human fibroadenoma (MED12, APC genomic mutations) as patient samples." (PMID 37328469, 2023). "We found an APC p.V1789L substitution in a 65-years-old female patient in whose medical history, in addition to the PTC, a previous duodenal ulcer and breast fibroadenoma were also reported." (PMID 33821390, 2021).
Cerebral ischemia (2 papers, 2012 to 2020). Restriction of arterial blood supply to the brain associated with insufficient oxygenation to support the metabolic requirements of the tissue. "PARK2-induced mitophagy is required for the APC-mediated neuroprotection to ischemic injury, which also extends the reperfusion window of cerebral ischemia." (PMID 33132849, 2020).
clear cell carcinoma (2 papers, 2020 to 2023).
Cognitive impairment (2 papers, 2018 to 2020). Abnormal cognition is characterized by deficits in thinking, reasoning, or remembering. "In this in vivo model, APC loss lead to excessive B-catenin and Wnt signal transduction in the forebrain as well as cognitive impairments and an autistic-like presentation." (PMID 32123549, 2020). "Synergistic impairment of multiple neuron types: excitatory pyramidal neurons, PV interneurons and SST interneurons, are likely responsible for the neurological phenotypes of social deficits, repetitive behaviors, cognitive impairments and chronic seizures seen in APC cKO mice." (PMID 30369876, 2018).
Cortisol Excess (2 papers, 2022 to 2026). "More importantly, identical directions of changes in APC, APS, and AT were observed in patients with Cushing's syndrome, in whom the risk of thromboembolism is significantly higher than in the general population." (PMID 35685509, 2022).
deep vein thrombosis (2 papers, 2021 to 2022). "Diminished anticoagulant activity and cytoprotective effects of certain APC variants can greatly increase the risk of thrombosis, especially when the vascular endothelium is inflamed or mechanically damaged." (PMID 33896796, 2021). "Notably, prothrombin (factor II) mutations are more often found in CSVT than in deep vein thrombosis (DVT), while FVL mutations (or APC-resistance) are more common in DVT compared to CSVT." (PMID 35888060, 2022).
depression (2 papers, 2016 to 2025). "Furthermore, APC mutant mice have abnormal brain function and behavior including depression-like behavior and decreased social interaction as well as autistic-like behaviors as manifested by increased repetitive behaviors and reduced social interest." (PMID 27777639, 2016).
dermatitis (2 papers, 2022 to 2023). An inflammatory process affecting the skin. "Other cell signaling pathways including cell cycle and NF-kB pathway (CCND1), autophagy (ATG16L2, ATG10), wnt/β-catenin (APC, GSK3β) and angiogenesis (EDN1) regulating genes were associated with RT related acute mucositis and dermatitis." (PMID 37954025, 2023).
endometrial tumor (2 papers, 2015 to 2022). "Genes with co-alterations notably enriched in KRASm subsets included STK11 in non-Sq NSCLC, PIK3CA and APC in CRC, and ARID1A, PTEN, and PIK3CA in endometrial tumors." (PMID 36494601, 2022).
epilepsy (2 papers, 2019). A brain disorder characterized by episodes of abnormally increased neuronal discharge resulting in transient episodes of sensory or motor neurological dysfunction, or psychic dysfunction. "Thus, Cdh1 Asp187Gly mutation is herein identified as a novel cause of APC/C‐Cdh1 inactivation triggering prenatal microcephaly, psychomotor retardation, and severe epilepsy in human." (PMID 31318984, 2019). "Our results indicate that APC/C‐Cdh1 loss of function caused by the Asp187Gly mutation impairs APC/C activity and underlies a new cause of prenatal microcephaly, psychomotor retardation, and epilepsy." (PMID 31318984, 2019).
esophagogastric adenocarcinoma (2 papers, 2004 to 2022). "In GEJ adenocarcinomas, very few APC and β-catenin mutations have been found." (PMID 14970870, 2004). "However, mutation analysis of APC and β-catenin in GEJ adenocarcinomas revealed mutations in only less than 7 and 3% of cases respectively." (PMID 14970870, 2004). "Since mutations in APC, β-catenin and AXIN1 do not play a major role in the frequent TCF/β-catenin activation in GEJ adenocarcinomas, other components should be considered." (PMID 14970870, 2004).
gastrointestinal carcinoma (2 papers, 2004 to 2017). "Inactivation of the APC gene is frequent in colorectal and other gastrointestinal carcinomas, usually by truncating mutations." (PMID 15476557, 2004). "In human gastrointestinal carcinoma, defects in the Wnt-APC pathway results in enhanced T-cell factor 4 (TCF4) transcriptional activation of c-MYC." (PMID 29232378, 2017).
hemophilia (2 papers, 2015 to 2024). Hemophilia is a genetic disorder characterized by spontaneous hemorrhage or prolonged bleeding due to factor VIII or IX deficiency. "Specifically, blocking the anticoagulant activity of APC has been shown to prevent joint bleeding in hemophilic mice, indicating that this approach holds promise for prophylactic therapy in hemophilia." (PMID 39408666, 2024). "The mixed model developed by us could be particularly useful for exploring such targeted interventions, providing a unique opportunity to understand how modifying one pathway (such as APC signaling) might mitigate the clinical manifestations of both hemophilia and SPCD." (PMID 39408666, 2024).
HIV-1 infection (2 papers, 2012 to 2017). The type species of lentivirus and the etiologic agent of acquired immunodeficiency syndrome (AIDS). "The same mAb clones used to inhibit HIV-1 infection were directly conjugated to different fluorescent dyes (anti-PDI- DyLight 488 and anti-Trx-APC), and used for Flow Cytometry analysis." (PMID 23206338, 2012). "Our current study thus uncovers a distinct function of APC in regulating the directional assembly/budding of HIV-1 and resultant cell-to-cell viral transmission, that could provide a new mode of therapeutic intervention against HIV-1 infection that targets virus–host interactions." (PMID 28134256, 2017).
injury (2 papers, 2006 to 2022). Damage inflicted on the body as the direct or indirect result of an external force, with or without disruption of structural continuity. "The effects of morroniside on the expression of the Wnt7a gene and adenomatous polyposis coli (APC) were assessed in rats with focal cerebral ischemia-reperfusion injury." (PMID 35563963, 2022).
ischemia (2 papers, 2016 to 2023). A hypoperfusion of the BLOOD through an organ or tissue caused by a PATHOLOGIC CONSTRICTION or obstruction of its BLOOD VESSELS, or an absence of BLOOD CIRCULATION. "Moreover, APC/C-Cdh1 down-regulation and subsequent glutaminase accumulation may contribute to the generation of excitotoxic environments in ischemia." (PMID 27514492, 2016).
leiomyoma (2 papers, 2024). A well-circumscribed benign smooth muscle neoplasm characterized by the presence of spindle cells with cigar-shaped nuclei, interlacing fascicles, and a whorled pattern. "We also examined the expression of APC and β-Catenin in paired myometrium and leiomyoma tissues and found that APC mRNA expression was reduced, while β-Catenin levels were upregulated in leiomyomas compared to matched myometrium." (PMID 39519092, 2024). "The decreased expression of LINCMD1 in leiomyoma tissue leads to an increase in miR-135b levels, which subsequently downregulates its target gene, APC." (PMID 39519092, 2024). "In one study, SFRP1 was significantly upregulated in leiomyomas relative to normal adjacent myometrium while other Wnt inhibitors such as APC, DKK1, and DKK3 were significantly downregulated." (PMID 37466765, 2024). "Previous studies have reported that the APC gene is a target of the miR-135 family in other cell types and plays a role in regulating Wnt/β-Catenin signaling, which is known to be dysregulated in leiomyomas." (PMID 39519092, 2024). "Additionally, APC protein levels were decreased in leiomyomas, while levels of non-phosphorylated β-Catenin at Ser45 (active form), total β-Catenin, and COL1A1 were increased." (PMID 39519092, 2024).
liver cirrhosis (2 papers, 2017 to 2018). "A two-step methylation sensitive PCR (MSP) analysis showed hyper-methylation of APC in 16 of the 26 (61.5%) HCC plasma samples compared to 2 out of16 (12.5%) in liver cirrhosis plasma samples suggesting a role for hyper-methylation in HCC." (PMID 28031532, 2017).
liver fibrosis (2 papers, 2018 to 2025). "APC, which negatively regulates the β-catenin pathway, was found to be associated with liver fibrosis." (PMID 29416678, 2018).
malignant parathyroid tumors (2 papers, 2021 to 2022). "These five patients with APC variants were relatively young at the time of diagnosis, and two were diagnosed with parathyroid cancer." (PMID 35586626, 2022). "Of interest, APC mutations were also observed in patients with parathyroid cancer and in those with FHH." (PMID 35586626, 2022). "Among the 13 parathyroid cancer patients in this study, two patients carried APC variants (c.890C>T [p.Thr297Ile] and c.5378C>G (p.Ala1793Gly]) and did not harbor any other pathogenic or likely pathogenic variants." (PMID 35586626, 2022). "Additionally, four patients with parathyroid cancer had VUSs: two APC variants (c.5378C>G [p.Ala1793Gly] and c.890C>T [p.Thr297Ile]), one WT1 variant (c.1139G>A [p.Arg380Gln]), and one PRKAR1A variant (c.567A>C [p.Glu189As])." (PMID 35586626, 2022). "APC gene variants have also been found in parathyroid cancers." (PMID 35586626, 2022). "Two out of five subjects with APC variants were diagnosed with parathyroid cancer." (PMID 35586626, 2022). "Interestingly, we identified one GCM2 variant (c.1162A>G [p.Lys388Glu]) and five APC variants that were previously reported in familial isolated hyperparathyroidism, benign sporadic PHPT, and parathyroid cancer." (PMID 35586626, 2022).
metastasis (2 papers, 2021 to 2023). The spread or migration of cancer cells from one part of the body (where they first appeared) to another.
mucinous neoplasm (2 papers, 2021 to 2023).
multiple endocrine neoplasia type 1 (2 papers, 2024 to 2025). An autosomal dominant tumor predisposition syndrome caused by pathogenic variants in the MEN1 gene, characterized by an increased risk of tumors of the parathyroid glands, pituitary gland, and foregut neuroendocrine tumors (most commonly pancreatic islet cells). "Notably, one patient with an APC gene mutation also harbored a SMAD4 (SMAD family member 4) gene mutation, while another patient with a SMAD4 gene mutation (n = 2, 14.29%) concurrently presented with a MEN1 (Multiple Endocrine Neoplasia Type 1) mutation (n = 1, 7.14%)." (PMID 39162366, 2024).
myopia (2 papers, 2015 to 2021). "We have recently described the APCMin mouse model of myopia in which a nonsense mutation of APC gene at codon 850 was introduced using random ethylnitrosourea (ENU) mutagenesis." (PMID 34259818, 2021). "Plasma from adult patients with myopia, myopic animal models including the adenomatous polyposis coli (APC) gene mutation mouse model, and the form deprivation (FD) induced mouse model of myopia were used." (PMID 34259818, 2021). "In this regard, there is some evidence that patients afflicted with familial adenomatous polyposis (FAP), havean adenomatous polyposis coli (APC) mutation and a higher incidence of myopia." (PMID 26495845, 2015). "In the present study, we examined in APCMin mice the association between myopia development and time dependent changes in refractive and biometric parameters to elucidate the functional role of an APC mutation (APCMin) in this process." (PMID 26495845, 2015). "The incomplete penetrance of myopia phenotype in these patients may be due to the differences in APC mutation sites, which has been shown to affect clinical manifestations." (PMID 26495845, 2015). "Furthermore, our findings prompt additional genetic studies on APC polymorphism and its related signaling pathways as they may be related to myopia development." (PMID 26495845, 2015). "This is the first study reporting that a rapid-onset and long-lasting increased expression of β-catenin and decreased expression of APC in form deprivation myopia (FDM) mice." (PMID 34259818, 2021). "In this study, we examined the alterations in the refractive and biometric parameters of APCMin mice to elucidate the functions of APC during myopia progression." (PMID 26495845, 2015).
neoplastic polyp (2 papers, 2022 to 2023). "Our recent study indicated that JRTs with GI neoplastic polyps harbor an identical germline variant in the APC gene, c.[462_463delinsTT], in a heterozygous state." (PMID 36288164, 2022).